MMP2 (matrix metallopeptidase 2)
Diseases named in the same sentence as MMP2 in open-access papers (continued):
Sharing a sentence is not in itself a finding about the gene and the disease.
chondrosarcoma (continued). "Therefore, MMP2 could be a possible therapeutic target to reduce local spread and invasion in chondrosarcomas." (PMID 29573200, 2018). "Furthermore, inhibition of MMP‐2 suppresses migration and metastasis of chondrosarcoma." (PMID 28672103, 2017). "In this study, whether miR-519d play a role in resistin-mediated metastasis was examined and found that resistin promotes tumor metastasis and MMP-2 expression by down-regulation of miR-519d expression through the AMPK/p38 signaling pathway in human chondrosarcoma." (PMID 25404641, 2015). "Therefore, HGF promoted migration of human chondrosarcoma cells through up-regulation of MMP-2." (PMID 23320110, 2013). "Therefore, reduction of MMP-2 expression may be a good target for preventing or treating chondrosarcoma metastasis." (PMID 23320110, 2013). "Similar to OS and ES, the expression of MMPs such as MMP-1, MMP-2, MMP-3, MMP-7, MMP-9, and MMP-14 is also found in biopsy specimens from patients with chondrosarcoma." (PMID 38138968, 2023). "The IHC results revealed significant increases in the levels of NGF and MMP-2 expression in the JJ012/NGF orthotopic model, confirming that NGF facilitated the metastasis of the chondrosarcoma to the mouse lung." (PMID 34283074, 2021). "A positive correlation observed between the MMP-2 and NGF staining intensity of the human chondrosarcoma tissue (r2 = 0.6) indicated that the levels of these proteins were associated with the progression of chondrosarcoma disease." (PMID 34283074, 2021). "Here, we found that visfatin facilitated cellular migration via matrix metalloproteinase-2 (MMP-2) production in human chondrosarcoma cells and overexpression of visfatin enhanced lung metastasis in a mouse model of chondrosarcoma." (PMID 34445345, 2021). "The IHC tissue array results revealed higher levels of NGF and MMP-2 expression in patients with a higher grade chondrosarcoma than in those with a lower grade disease; the levels of NGF and MMP-2 expression were reflected by the tumor stage." (PMID 34283074, 2021). "IHC results revealed significant increases visfatin and MMP-2 expression in the JJ012/visfatin orthotopic model, confirming that visfatin facilitates the metastasis of chondrosarcoma to the mouse lung." (PMID 34445345, 2021). "In vitro, rCCL3 induced MMP-2 expression and migration in the JJ012 chondrosarcoma cell line, which was mediated by AMP-activated protein kinase (AMPK), p38 MAPK and nuclear factor kappa B (NF-κB)." (PMID 29361725, 2018). "Herein, we showed that S1P inhibits MMP‐2 expression through the upregulation of TIMP‐3, thereby suppressing human chondrosarcoma cell migration." (PMID 28672103, 2017). "Thus, manipulation of MMP‐2 may regulate the chondrosarcoma metastasis." (PMID 28672103, 2017). "Therefore, MMP-2 may a key regulator during metastasis of chondrosarcoma." (PMID 25404641, 2015). "Previous studies have demonstrated the expression of MMP-1, MMP-2, MMP-3, MMP-9, and MMP-13 in human chondrosarcoma cells." (PMID 24047437, 2013). "In human chondrosarcoma cell lines, MMP-1, MMP-2, MMP-3, MMP-9, and MMP-13 demonstrate increased expression." (PMID 23320110, 2013). "Pre-treatment of chondrosarcoma cells for 30 min with SB203580 or transfection with the p38 mutant for 24 h markedly attenuated the CCL3-induced migration activity and MMP-2 expression." (PMID 24047437, 2013). "In chondrosarcoma cells, tumor necrosis factor (TNF)-α had a stimulatory effect on MMP-9 and insignificant effect on MMP-2 and interleukin (IL)-1β stimulated MMP-9 and MMP-2." (PMID 24085323, 2013). "It has also been reported that MMP-2 plays a critical role in ECM turnover and cell-cell interactions as well as metastases of chondrosarcomas." (PMID 24047437, 2013). "However, the expression of CCL3, CCR5 and MMP-2 in chondrosarcoma is still unknown." (PMID 24047437, 2013). "A previous study showed that MMP-1, MMP-2, MMP-3, MMP-9, and MMP-13 were expressed in high quantities in human chondrosarcoma cells." (PMID 23892595, 2013).
chondrosarcoma (continued). "Pre-treatment of chondrosarcoma cells with CCR5 mAb or inhibitor blocked CCL3-induced cell migration and reduced MMP-2 expression." (PMID 24047437, 2013). "Our study demonstrated that HGF increases the activity of MMP-2 via c-Met receptor-, PI3K-, Akt-, PKCδ-, IKKα/β-, and NF-κB-dependent pathways and enhanced the migration of human chondrosarcoma cells." (PMID 23320110, 2013). "Studies have shown that MMP-1, MMP-2, MMP-3, MMP-9, and MMP-13 exhibit high degrees of expression in human chondrosarcoma cells." (PMID 23892595, 2013). "In other tumors and chondrosarcoma, CXCR4 signaling upregulates other MMPs such as MMP-2, 8 and -9 and -13." (PMID 20102637, 2010). "In Chondrosarcoma, low levels of miR-145 lead to the overexpression of SOX9, which in turn activates ETV5, a transcription factor involved in metastasis, ultimately leading to the increased expression of MMP-2 and increased extracellular matrix degradation." (PMID 40429954, 2025). "Furthermore, while the EMT markers including Slug, MMP9, MMP2, CD44, N-Cadherin, and vimentin were suppressed by BTZ concomitant increased expression of E-Cadherin was detected in chondrosarcoma cells." (PMID 33674562, 2021). "WISP1 enhances cell migration by increasing MMP-2 expression by regulating the α5β1 integrin receptor, FAK, MEK, ERK, p65 and NF-κB signal transduction pathway in chondrosarcoma, suggesting that WISP1 may play an oncogenic role in chondrosarcoma." (PMID 30651114, 2019). "MMP-1, MMP-2, MMP-3, MMP-7, MMP-9 and MMP-13 are frequently expressed in chondrosarcoma tissues." (PMID 29361725, 2018). "MMP-1, MMP-2, MMP-3, MMP-9, and MMP-13 are expressed in human chondrosarcoma cells." (PMID 25404641, 2015). "RT-qPCR analysis of resistin, MMP-2, and miR-519d performed in chondrosarcoma and normal samples showed a positive correlation between resistin and MMP-2; and negative correlations between resistin and miR-519d, MMP-2 and miR-519d." (PMID 25404641, 2015). "Upregulation of MMP2 and MT1-MMP has been reported in high-grade malignant cartilaginous tumors, as well as in the high-grade dedifferentiated component of dedifferentiated chondrosarcoma." (PMID 23227977, 2012). "The increase in MMP-13 expression may be necessary for the activation of other MMPs that have previously been identified in chondrosarcoma such as MMP-2 and MMP-9 it is also activated by MMP-2, MMP-3, and MTI-MMP." (PMID 18554405, 2008). "In the case of studies and MMP-2 and MMP-14, the expression of this enzyme was confirmed in various molecular subtypes of chondrosarcoma: clear-cell chondrosarcomas, mesenchymal chondrosarcomas, conventional chondrosarcomas, and dedifferentiated chondrosarcomas." (PMID 38138968, 2023). "At the protein level, TIMP2 expression correlates with that of MMP2 and MMP14 in chondrosarcoma, all three proteins displaying elevated levels in high-grade anaplastic components compared to low-grade components of de-differentiated and conventional chondrosarcoma." (PMID 31466240, 2019). "The expression of MMP-2 and MMP-14 was not significantly different between enchondroma and chondrosarcoma." (PMID 38138968, 2023).
chronic kidney disease (36 papers, 2013 to 2026). Impairment of the renal function secondary to chronic kidney damage persisting for three or more months. "Increased MMP-2 in the serum and urine has been associated with progressive kidney fibrosis in chronic kidney disease." (PMID 39946431, 2025). "In adults with chronic kidney diseases, increased serum levels of cathepsin S and MMP-2 are associated with aortic stiffening." (PMID 24743169, 2014). "In a uremic mouse model of chronic kidney disease, a vascular smooth muscle cell phenotype change, reflected by the loss of SMA and other smooth muscle markers and the upregulation of MMP-2, preceded cell loss and arterial medial calcification." (PMID 38984107, 2024). "MMP-2 was shown to be a predictor of diabetic renal fibrosis leading to the progression of chronic kidney disease." (PMID 39769454, 2024). "Another rat model, in this case displaying vascular calcification in chronic kidney diseases, exhibited a raised MMP-2 and MMP-9 expression and activity upon arterial calcification." (PMID 37189419, 2023). "Knockdown of Rab7 significantly alleviated the renal hypoxia in chronic kidney disease through regulation of MMP-2." (PMID 34695807, 2021). "MMP-2 has been related to the pathogenesis of chronic kidney disease, and its increased expression generates kidney damage as a result of ischemia–reperfusion injury." (PMID 33419373, 2020). "In the advanced stage of chronic kidney disease, the activity of MMP-2 and MMP-9 is decreased and, in this late period, the fibrosis is difficult to reverse." (PMID 32403389, 2020). "Matrix metalloproteinases (MMPs), in particular MMP9 and MMP2, are up-regulated in chronic kidney diseases and they sustain fibrosis via TGF-beta pathway." (PMID 30546836, 2018). "This study revealed significantly higher levels of MMP-2 in patients with chronic kidney disease in comparison to the control group." (PMID 26843213, 2016). "Statistically higher levels of MMP-2 in patients with chronic kidney disease are observed as compared to the control group (p = 0.002) were observed in this study." (PMID 26843213, 2016). "In a clinical study at 18 centers between 2006 and 2013, effluent TN-C and MMP-2 levels were quantified in 182 PD patients with end-stage renal disease." (PMID 26770971, 2015). "Recently, we have found that serum MMP-2 levels are one of the independent determinants of proteinuria in patients with chronic kidney disease." (PMID 25143788, 2014). "Analysis of results of this study revealed significantly higher levels of MMP-2 in patients with chronic kidney disease in comparison to the control group." (PMID 25145866, 2014). "Interestingly, MMP2 levels were significantly elevated in patients with chronic kidney diseases and increased significantly in patients with a dropped crystalline lens." (PMID 41009516, 2025). "Patients who had chronic kidney disease had higher levels of MMP2 (17.3 ng/mL, p = 0.039)." (PMID 41009516, 2025). "Indeed, increased levels of MMP-2 in the sera have been seen in animal models of chronic kidney disease and in humans with chronic kidney disease." (PMID 39946431, 2025). "MMP2 plays a key role in the development of chronic kidney disease by remodeling the extracellular matrix, distorting the structure of the glomerular basement membrane, contributing to the development of tubulointerstitial fibrosis and leading to progressive kidney injury." (PMID 36896170, 2023). "The aggravation of renal interstitial fibrosis in the advanced-stage of chronic kidney disease is related to decreased matrix metalloproteinase-2 (MMP-2) activity, which is induced by hypoxia in the kidney; however, the specific mechanism remains unclear." (PMID 29462885, 2018). "Arteries of dialyzed chronic kidney disease patients compared to those of non-dialyzed chronic kidney disease patients and kidney donors showed higher MMP-2 activity, which was associated with lower elastic fiber content and greater arterial stiffness." (PMID 29070037, 2017).
chronic kidney disease (continued). "Moreover, it has been suggested that elevated levels of MMP-2 and decreased concentration of MMP-9 are associated with the development of chronic kidney disease." (PMID 26843213, 2016). "Furthermore, we have recently found that serum MMP-2 levels were positively associated with proteinuria and inversely correlated with estimated GFR in patients with chronic kidney disease." (PMID 25143788, 2014). "As MMP-2 has been identified as a key player in fibrotic diseases and ECM degradation, its role in both acute and chronic kidney disease has been widely studied." (PMID 39769454, 2024). "This imbalance in MMP-2 activity accelerates renal fibrosis, impairing kidney function and facilitating the progression of CKD to end-stage renal disease." (PMID 39769454, 2024). "Recent studies have shed light on the role of MMP-2 in acute kidney injury (AKI) and its transition to chronic kidney disease (CKD), emphasizing its involvement in maladaptive repair mechanisms." (PMID 39769454, 2024). "It has been found that MMP-2 and MMP-9 expressions are dysregulated in both acute and chronic kidney diseases." (PMID 37287620, 2023). "Several studies have shown elevated levels of MMP-2 and TIMP-2 in the serum of patients with chronic kidney disease (CKD)." (PMID 33419373, 2020). "Both MMP-2 and MMP-9 are highly expressed in the tubular compartment in animal models with chronic kidney disease, and they were also found in the serum of patients with chronic kidney disease." (PMID 24719498, 2014). "The serum levels of MMP-2 and TIMP-2 are elevated in chronic kidney disease patients." (PMID 37867197, 2023). "Apart from the PTGER3 gene, matrix metalloproteinase-2 (MMP-2) is also differentially methylated in diabetic patients with the end-stage renal disease compared with those without nephropathy." (PMID 33435900, 2021). "In patients with chronic kidney diseases, creatinine level was positively correlated with MMP-2 (r = 0.39), but in diabetic patients it was negative correlation (r = − 0.72)." (PMID 33435900, 2021). "Metalloproteinase-2 (MMP-2) and metalloproteinase-9 (MMP-9) are members of the gelatinase family and were demonstrated in animal models and in vitro systems as important mechanisms of fibrosis in progressive chronic kidney disease." (PMID 24719498, 2014). "In a chronic kidney disease (CKD) mouse model, elevated systemic urea led to downregulation of Cldn5 in brain endothelial cells, with concomitant disruption of the BBB mediated by MMP2 activation." (PMID 40940757, 2025). "Moreover, MMP-2 and TIMP-2 concentrations were much higher in patients with chronic kidney disease, suggesting that these factors may be involved in the pathogenesis of CAD in patients with CKD." (PMID 25145866, 2014). "In a rat model of adenine-induced chronic kidney disease (CKD), adropin was found to reduce urine protein levels and 24-hour urine volume and downregulate inflammatory markers such as TIMP-1, IL-33, and MMP-2, suggesting a protective effect against renal damage and inflammation." (PMID 39766320, 2024). "Statistically significant results were found also for the MMP-2/TIMP-2 ratio, with the lowest values in the control group and the highest in patients with stage IV chronic kidney disease as well as in patients with stage V CKD and on dialysis." (PMID 26843213, 2016). "Circulating matrix metalloproteinase (MMP)-2, -3 and -9 are well recognized in predicting cardiovascular outcome in coronary artery disease (CAD), but their risks for chronic kidney disease (CKD) are lacking." (PMID 23922934, 2013).
colitis (36 papers, 2013 to 2026). Inflammation of the colon. "Another study reported that MMP-2-deficient mice were more resilient to acute dextran sulfate sodium (DSS) colitis and were characterized by better clinical, micro-, and macroscopic outcomes." (PMID 38338780, 2024). "MMP9 and MMP2 double-deficient susceptible mice are resistant to STm-induced colitis demonstrating that MMP-9 overrides the protective effect of MMP-2 in mediating inflammation and tissue damage." (PMID 35733975, 2022). "In contrast, MMP-2 deficient mice are highly susceptible to STm-induced colitis." (PMID 35733975, 2022). "Post-colitis (therapeutic) EP administration produced greater suppression of MMP-2, MMP-9, NF-κB, HMGB1 and iNOS, along with superior restoration of TAC (P < 0.05), indicating timing-dependent modulation of inflammatory and matrix degradation pathways." (PMID 42307112, 2026). "In the present study, MMP-3 and MMP-2 were shown to be upregulated in our DSS-induced colitis model, consistent with earlier studies." (PMID 40862456, 2025). "CGS-27023-A (MMI-270), a sulfonamide derivative that has a broad spectrum of inhibition for MMPs, has been shown to attenuate colonic mucosal injury in TNBS-induced colitis in rats by reducing MMP-2 and MMP-9 expression." (PMID 33802197, 2021). "In vivo studies showed that the MMPI maintained its bioactivities when administered orally and significantly reduced colitis symptoms, along with a very significant inhibition of MMP-2 and -9 activities." (PMID 34948082, 2021). "The expression of TIMP-1 was significantly upregulated, and MMP2/9 were significantly downregulated in the colonic tissue of mice with TNBS-induced colitis." (PMID 35002710, 2021). "Epithelial-derived MMP-9 is an important mediator of tissue injury in colitis, whereas MMP-2 protects against tissue damage and maintains gut barrier function." (PMID 31437166, 2019). "It was also shown that the gelatinases play opposing roles in intestinal inflammation where MMP-9 can potentiate colitis but MMP-2 participates in maintaining epithelial barrier function to prevent the initiation of colitis." (PMID 25948887, 2015). "In this model, the MMP-2-ablated mice developed a more severe colitis than the control animals indicating that MMP-2 has a protective role against developing colitis and may explain elevated levels in response to treatment." (PMID 28522897, 2017). "MMP2 inhibition in the context of colitis may have detrimental consequences, as MMP2 knockout mice demonstrate exacerbated DSS-induced colitis." (PMID 25961845, 2015). "It has been proven that the overexpression of MMP-2 in cultured intestinal epithelial cells determines the integrity of the protective barrier whereas its downregulation affects the sensitivity of the mucosa and may determine the occurrence of colitis." (PMID 27034654, 2016). "Upregulation of several secreted MMPs has been reported in the colonic mucosa of dogs with colitis, including MMP-1, MMP-3, and MMP-13, as well as MMP-2 and MMP-9." (PMID 35751094, 2022). "MMP-2 and MMP-9 levels were consistently up-regulated during active flare-ups of IBD in patients and an animal colitis model." (PMID 36289761, 2022). "Previous studies suggest that both MMP-2 and MMP-9 are mediators of tissue damage; the first ones maintain the intestine barrier function and the second ones participate in colitis." (PMID 36140716, 2022). "Most MMPs, such as MMP-2, MMP-3, MMP-7, MMP-9, MMP-10, MMP-12, and MMP-13 are increased in colitis and CAC." (PMID 36776395, 2022). "MSC-CM administered intraperitoneally has demonstrated to improve the symptoms of experimental colitis and decrease TNF-α and MMP2 expression in mice." (PMID 36012170, 2022). "The overexpression of inflammatory-related proteins, MMP-2, MMP-9 and MMP-13 has been reported to be involved in colon damage during colitis." (PMID 35159480, 2022). "Elevated levels of MMP-2, -3, -7, and -9 mRNA and proteins were observed in mice with DSS-induced colitis." (PMID 23841050, 2013).